MGMT (O-6-methylguanine-DNA methyltransferase)
Diseases named in the same sentence as MGMT in open-access papers (continued):
Sharing a sentence is not in itself a finding about the gene and the disease.
glioblastoma (continued). "Conversely, up-regulation of miR-125b is associated with poor prognosis in HER2-positive gastric cancer and in MGMT promoter-unmethylated glioblastoma." (PMID 31394878, 2019). "Determination of MGMT promoter methylation is widely used in clinical routines as a predictive biomarker to assess treatment prospects of glioblastoma with the alkylating agent temozolomide." (PMID 34991275, 2019). "Some such changes have already shown clinical relevance, such as BRCA1 in breast cancer, MGMT in glioblastoma multiform, and SEPT9, which has been approved by the Food and Drug Administration (FDA) for the diagnosis of colon cancer." (PMID 31452839, 2019). "Patients with MGMT promoter methylation and a glioblastoma showed an OS in between (median OS 15 months)." (PMID 31623667, 2019). "It has been reported that both O6BG-Glu and O6BTG-Glu are highly effective at inhibiting MGMT in several cancer cell lines, including T98G glioblastoma." (PMID 32010632, 2019). "The MGMT activity was significant, however, in patients with primary glioblastomas and recurrences that received RT plus alkylating agent therapy." (PMID 32010632, 2019). "In the clinic, the most relevant epigenetic marker is O-6-Methylguanine-DNA Methyltransferase (MGMT) as a predictor of response to chemotherapy in glioblastoma." (PMID 31817025, 2019). "Checkmate 498 is comparing the efficacy of nivolumab + RT versus the standard treatment of TMZ + RT in newly diagnosed glioblastoma patients with unmethylated MGMT." (PMID 30777100, 2019). "Kalkan and colleagues (2015) assessed MGMT promoter methylation status on 40 primary glioblastoma from Turkish patients." (PMID 30717206, 2019). "Future studies will focus on methylated MGMT glioblastoma patients and the ability for the radiologist to visually determine analogs to the radiomic characteristics that we have identified." (PMID 30774763, 2019). "This has resulted in attempts at therapeutic stratification of glioblastoma based on MGMT methylation status." (PMID 31083587, 2019). "They found that MGMT activity increased after treatment, and methylation of MGMT promoter was detected in 39% primary tumors, while only 5.3% recurrent glioblastomas displayed MGMT promoter methylation." (PMID 32010632, 2019). "Methylation of the O6-methylguanine DNA methyltransferase (MGMT) promoter has emerged as strong prognostic factor in the therapy of glioblastoma multiforme." (PMID 31766430, 2019). "Overexpression of miR-370-3p impairs glioblastoma multiforme resistance to temozolomide via affecting MGMT expression." (PMID 31703640, 2019). "Further population-based studies are needed to assess the prognostic value of the MGMT promoter methylation status for patients with primary glioblastoma." (PMID 30717206, 2019). "Materials and methods: A cohort of 30 Serbian primary glioblastoma patients treated with radiation therapy and chemotherapy were analyzed for MGMT promoter methylation and correlated with clinical data." (PMID 30717206, 2019). "Among the already identified and routinely implemented epigenetic marker genes is the programmatic promoter DNA methylation of the DNA repair gene MGMT in the treatment of glioblastoma by temozolomide (an alkylating agent)." (PMID 34991275, 2019). "Checkmate 548 is comparing the efficacy of nivolumab + RT + TMZ versus RT + TMZ in newly diagnosed glioblastoma patients with methylated MGMT." (PMID 30777100, 2019). "In fact, in the present study, we observed a slight degree of MGMT methylation in normal brain, lymphocyte, and colon tissue samples, although all values were under the minimum cut-off identified for glioblastoma tissue." (PMID 31366977, 2019). "We have assessed MGMT methylation status in blood and tissue samples from unresected glioblastoma patients who had been included in the randomized GENOM-009 trial." (PMID 31366977, 2019).
glioblastoma (continued). "As a matter of fact, temozolomide and TTFields have been reported to synergistically accelerate cell death of irradiated glioblastoma cells in vitro, however, independently of MGMT status." (PMID 30669316, 2019). "The main goal of our study was to determine MGMT promoter methylation and its relevance for the prediction and prognosis of clinical outcomes of the Serbian population with glioblastoma." (PMID 30717206, 2019). "MGMT methylation status is a well-known predictive and prognostic factor in glioblastoma, and its assessment at the time of diagnosis is an important factor both for clinical trials and for deciding on the optimal treatment strategy." (PMID 31366977, 2019). "Methylation at the O6-Methylguanine-DNA Methyltransferase (MGMT) promoter is of particular interest given its utility epigenetic modification in determining response to temozolomide (TMZ) in glioblastoma." (PMID 31139150, 2019). "Happold and coworkers analyzed glioblastoma cancer stem cells and described NF-κB as a positive regulator of MGMT (O6-methylguanine DNA methyltransferase) mediated by NF-κB p65." (PMID 31083587, 2019). "Temozolomide (TMZ) is active against glioblastomas (GBM) in which the O6-methylguanine-DNA methyltransferase (MGMT) gene is silenced." (PMID 30153289, 2018). "The analysis of subsets of glioblastoma patients helped to identify MGMT-methylated tumors responding to temozolomide treatment." (PMID 30279357, 2018). "The aim of this study is to evaluate the prevalence of MGMT methylation in Peruvian glioblastoma cases." (PMID 29515653, 2018). "Various clinical trials are evaluating the PARP1 inhibitor (Olaparib) in combination with radiotherapy and/or temozolomide in glioblastoma patients subdivided according to the MGMT methylation status." (PMID 30279357, 2018). "Here, we now demonstrate that LGK974 acts synergistically with TMZ chemotherapy to reduce cell viability in both MGMT promoter-methylated and unmethylated glioblastoma neurosphere cell lines." (PMID 29854309, 2018). "ADC and rCBF are promising imaging biomarkers in clinical routine to predict the MGMT promoter methylation in primary glioblastoma patients." (PMID 29467012, 2018). "Testing methylation of MGMT promoter in glioblastoma has been implemented in centres of reference in cancer worldwide and our results confirm the prognostic value of the methylation status in our population." (PMID 29515653, 2018). "A recent study reported a detailed analysis of genetic (mutations and copy number alterations) and epigenetic (methylation profile) of IDHWT glioblastomas, subdivided according to MGMT promoter methylation." (PMID 30279357, 2018). "Huang and colleagues showed that RES decreased the expression of the MGMT protein in glioblastoma cells, by suppressing the activation of the NF-κB transcription factor essential for MGMT activation." (PMID 30524273, 2018). "The present study describes, for the first time to our knowledge, a rate of MGMT-promoter methylation status in Peruvian cases of glioblastoma (46%) that is in the range described for Caucasian race (36–50%)." (PMID 29515653, 2018). "The aim of the study was to selectively deliver BG to the glioblastoma in mice, inhibit the DNA repair protein O6-methylguanine-DNA methyltransferase (MGMT), and overcome Temozolomide resistance." (PMID 30619758, 2018). "The PredictMDx test is a commercially available epigenetic assay for testing methylation status of the MGMT gene and has impact on decision making especially for the patients with newly diagnosed glioblastoma." (PMID 30374421, 2018). "•PARADIGM-2 comprises two parallel phase I, dose escalation studies of the PARP inhibitor olaparib in combination with radiotherapy (for MGMT unmethylated patients) and radiotherapy-temozolomide (for MGMT methylated patients) in newly diagnosed glioblastoma." (PMID 29594237, 2018).
glioblastoma (continued). "In fact, there is discordance between MGMT promoter methylation and MGMT methylation and MGMT expression in glioblastomas with WT-MGMT coding sequence." (PMID 30279357, 2018). "In this study, we investigated the value of features from structural and advanced imagings in predicting the methylation of MGMT promoter in primary glioblastoma patients." (PMID 29467012, 2018). "In glioblastoma, we find a high incidence of MGMT promoter methylation, which is assumed to allow for higher tumour flexibility by increasing the rate of (unrepaired) mutations." (PMID 29371599, 2018). "PARADIGM-2 is a phase I dose escalation study evaluating olaparib plus radiotherapy ± temozolomide in newly diagnosed glioblastoma, using MGMT methylation status to stratify patients and inform treatment schedules." (PMID 29594237, 2018). "We applied real-time semi-quantitative methylation-specific polymerase chain reaction (SQ-MSP) of the MGMT gene promoter region to 84 glioblastoma patients." (PMID 29963232, 2018). "Since hypomethylation of MGMT confers the resistance of glioblastoma to TMZ, our data provides a logical rationale for the co-treatment of TMZ with lipoic acid." (PMID 29925764, 2018). "Promoter status of O6-methylguanine-DNA methyltransferase (MGMT) has been widely established as a clinically relevant factor in glioblastoma (GBM) patients." (PMID 29619003, 2018). "For example, a few studies have documented intratumoral heterogeneity with regard to MGMT status in patient samples derived from melanoma, as well as glioblastoma." (PMID 30274152, 2018). "MGMT-promoter methylation frequency in Peruvian glioblastoma is similar to that reported in other populations and the detection test has been standardised." (PMID 29515653, 2018). "O6-methylguanine–DNA methyltransferase (MGMT) promoter methylation predicts the outcome and response to alkylating chemotherapy in glioblastoma." (PMID 29515653, 2018). "The percentage of tumors with methylated MGMT is lower than in glioblastoma, and clinical studies with melanoma patients concluded that MGMT promoter methylation status did not correlate with clinical outcome after TMZ." (PMID 30274152, 2018). "An article on meta-analysis of bevacizumab plus temozolomide- radiotherapy for newly diagnosed glioblastoma with different O6-methylguanine–DNA methyltransferase (MGMT) methylation status was published." (PMID 28915674, 2017). "The intracellular levels of the alkylating enzyme MGMT interfere with TMZ response in patients with glioblastoma multiform." (PMID 28831025, 2017). "Multivariate analyses of progression-free survival and overall survival stratified by rs1625649 genotypes in patients with MGMT methylated glioblastoma." (PMID 29036186, 2017). "In glioblastoma, subjects with MGMT hypermethylation have significantly longer survival rates after chemoradiotherapy." (PMID 28752860, 2017). "A model including BTV, MGMT protein status, PS and age can estimate the probabilities of OS for glioblastoma patients and can, if validated, be implemented in the clinical practice for treatment stratification." (PMID 27554774, 2017). "The aim of this study was to evaluate the clinical significance of SNPs in the MGMT promoter region of glioblastoma." (PMID 29036186, 2017). "In conclusion, the MGMT promoter homozygous rs1625649 (AA genotype) was found to correlate with a better PFS in patients with MGMT methylated glioblastoma." (PMID 29036186, 2017). "Rs1625649 was the only polymorphic SNP located at the MGMT promoter region in 37.5% of glioblastomas." (PMID 29036186, 2017). "MGMT methylation status was available for almost the whole population, as well as all classical glioblastoma prognostic factors." (PMID 28424082, 2017).
glioblastoma (continued). "Former studies on prognostic factors for glioblastoma patients treated with standard therapy suggests that age, MGMT protein status, use of corticosteroids and performance status are associated with OS." (PMID 27554774, 2017). "One of the main mechanisms of glioblastoma resistance to TMZ is thought to be mediated by O6-methylguanine-DNA methyltransferase (MGMT)." (PMID 26872471, 2016). "To verify the down-modulation of MGMT expression by increasing the intracellular concentration of the candidate miRNAs in vitro, we selected a glioblastoma cell line expressing costitutively a high level of MGMT mRNA." (PMID 27057640, 2016). "We screened the expression of 1,205 miRNAs in glioblastoma tissue samples with differential expression of MGMT transcript." (PMID 27057640, 2016). "In conclusion, our results showed that the three-gene signature has prognosis value for patients with MGMT promoter-methylated glioblastomas." (PMID 27588397, 2016). "It is well established that MGMT methylation is a promising predictor of prolonged prognosis in patients with glioblastoma receiving temozolomide." (PMID 27643594, 2016). "Increasing evidence demonstrates that the O6-methylguanine methyltransferase (MGMT), whose function is repairing the mutagenic DNA lesion O6-methylguanine back to guanine, is expressed in 80% of glioblastoma patients." (PMID 26880988, 2016). "Recent studies suggest that miRNA regulation additionally contribute to the expression pattern of MGMT in clinical glioblastoma specimens." (PMID 27057640, 2016). "We analyzed glioblastoma cell lines with known MGMT activity and formalin-fixed samples from IDH1 wild-type high-grade glioma patients (WHO grade III/IV) treated with radiation and temozolomide by HRM, MSP, and pyrosequencing." (PMID 27158275, 2016). "Other signaling pathways such as (JNK) or microenvironment conditions (hypoxia) can also contribute to chemoresistance of glioblastoma by upregulating the expression of MGMT." (PMID 26880988, 2016). "The series of miRNAs proposed by previous and our work suggest a cooperative interaction of different miRNAs in MGMT-regulation the glioblastoma tissues in vivo." (PMID 27057640, 2016). "For our candidate gene approach we selected 14 genes with a high proportion of high 5 hmC sites in a given gene region and a gene with an established relationship to glioblastoma survival, MGMT." (PMID 27886174, 2016). "Transfection of the T98G glioblastoma cell line with pre-miR-124-3p, -127-3p, -181d-5p and -409-3p reduced the MGMT mRNA at different extents, the most significant down-modulation being obtained with the pre-miR-181d-5p and -409-3p." (PMID 27057640, 2016). "In glioblastoma patients, methylation of the O6-methylguanine methyltransferase (MGMT) gene promoter is positively correlated with an increased effectiveness of current standard of care." (PMID 27277032, 2016). "Validation of the candidate miRNAs in terms of quantitative expression and effect of MGMT modulation in glioblastoma cell line in vitro identified a novel role for miR-409 in the epigenetic regulation of expression of MGMT gene." (PMID 27057640, 2016). "A currently known example would be resistance to chemotherapy in glioblastoma cells exhibiting MGMT methylation." (PMID 27036027, 2016). "Understanding the molecular mechanism involved in the regulation of MGMT expression/function is vital for identification of therapeutic targets; however, signaling pathways controlling MGMT in glioblastoma cells remain poorly characterized." (PMID 28000777, 2016). "Currently Cilengitide has entered in phase II trials with glioblastoma patients with unmethyleted MGMT gene promoter." (PMID 26936767, 2016).
glioblastoma (continued). "Unfortunately, recent results from phase III clinical trials showed a non-significant increase in patient survival in patients diagnosed with glioblastoma and methylated MGMT (O6-methylguanine–DNA methyltransferase) gene promoter." (PMID 26936767, 2016). "In conclusion, our results showed that the signature has prognostic value for patients with MGMT promoter-methylated glioblastomas based on bioinformatics analysis." (PMID 27588397, 2016). "The prognostic value of the status of O6-methylguanine-DNA methyltransferase (MGMT) promoter methylation measured by pyrosequencing assay (PSQ) among glioblastoma (GBM) patients was examined in meta-analysis." (PMID 27733166, 2016). "The best estimate suggest that MGMT promoter methylation status accounts for ∼50% of variation in MGMT expression in clinical glioblastoma specimens." (PMID 27057640, 2016). "In the current study, multiple spatially distinct biopsies were taken from the same glioblastoma tumor in order to investigate intratumoral heterogeneity in key glioma biomarkers including MGMT promoter methylation and transcriptional subtype." (PMID 26940435, 2016). "MGMT plays an important role in resistance to TMZ, and glioblastoma patients carrying a methylated MGMT promoter exhibit improved progression-free and overall survival after treatment with alkylating agents." (PMID 26880988, 2016). "The levels of expression of O6-methylguanine-DNA methyltransferase (MGMT) are relevant in predicting the response to the alkylating chemotherapy in patients affected by glioblastoma." (PMID 27057640, 2016). "MGMT methylation has been used as a biomarker of response to alkylating agents in glioblastoma patients." (PMID 27886174, 2016). "Transfection of the MGMT expressing T98G glioblastoma cells with the pre-miRNAs increasing the intracellular concentrations of miR-181d-5p, miR-409-3p, miR-124-3p and miR-127-3p produce reduced MGMT protein." (PMID 27057640, 2016). "Among possible mechanisms, O6-methylguanine DNA methyltransferase (MGMT) expression has been well documented as the clinically most relevant mechanism of resistance against TMZ-based glioblastoma therapies." (PMID 28000777, 2016). "Promoter methylation status of the DNA repair enzyme O6-methylguanine DNA methyltransferase (MGMT) is the most important clinical biomarker in glioblastoma, predicting for therapeutic response." (PMID 26940435, 2016). "In a recent review about MGMT methylation pyrosequencing in glioblastoma, more than 20 studies have been reported." (PMID 27542245, 2016). "MGMT gene silencing through promotor methylation confers sensitivity to the alkylating agents in glioblastoma." (PMID 25906748, 2015). "Promoter methylation represents one of the major factors silencing MGMT gene expression and predicts a favorable outcome in patients with glioblastomas exposed to TMZ." (PMID 26400193, 2015). "For example, it has recently been reported that MGMT methylation status was only predictive in glioblastoma cases with a classical transcriptional gene signature." (PMID 25785247, 2015). "Previous studies have targeted the transcriptional activity of SP1 to regulate the expression of MGMT and other genes for glioblastoma therapy." (PMID 25514975, 2015). "Previous studies have documented that O6 methylguanine-DNA-methyl transferase (MGMT) correlates with the response of glioblastomas to TMZ." (PMID 26400193, 2015). "Currently, O6-methylguanine-DNA methyltransferase(MGMT) promoter methylation is the most convincing predictive biomarker for temozolomide (TMZ) response in patients with glioblastoma multiforme (GBM)." (PMID 25890369, 2015). "The NOA-08 and Nordic clinical trials in elderly patients presenting with primary glioblastoma have also shown that a methylated MGMT promoter is predictive and prognostic in response to therapy." (PMID 25785247, 2015).